FOXO1 (forkhead box O1)
Diseases named in the same sentence as FOXO1 in open-access papers (continued):
Sharing a sentence is not in itself a finding about the gene and the disease.
ovarian carcinoma (continued). "The LGR5, FOXO1, and miR-340 genes can be targeted for early diagnosis and more accurate treatment of ovarian cancer and may prevent some of the ovarian cancer complications such as infertility." (PMID 33718760, 2021). "Our results further show the mechanisms underlying the stimulation of proliferation and stemness of ovarian cancer cells by CD83, involving interaction with MAP3K7 and activation of MAPK signaling pathway, as well as downstream FOXO1/p21/CDK2/Cyclin B1 and STAT3/DKK1 cascades." (PMID 32823589, 2020). "TNF, ESR1, MUC1 and FOXO1 are our candidate genes that might take part in ovarian cancer progression in an epigenetic approach, TNF, ESR1 and FOXO1 may serve as potential markers for ovarian cancer prognosis evaluation." (PMID 32192517, 2020). "For the HEDW hub genes, FOXO1 was significantly lower in ovarian cancer tissues than that in normal tissues, indicating it might participate in ovarian cancer development with a different approach." (PMID 32192517, 2020). "MiR-27a enhances ovarian cancer development via repressing FOXO1." (PMID 32469064, 2020). "FOXO1 was significantly lower in ovarian cancer samples than that in normal samples." (PMID 32192517, 2020). "Indeed, selinexor-induced enrichment of FoxO1 nuclear localization was exploited to increase cisplatin sensitivity in ovarian carcinoma cells." (PMID 30646603, 2019). "Moreover, elevated FoxO1 expression and its nuclear localization were observed in taxane-induced drug resistance in ovarian cancer patients." (PMID 30559384, 2018). "Interestingly, FOXO1 was also shown to induce cellular senescence of ovarian cancer cells treated with progesterone." (PMID 29227245, 2017). "FoxO1 and FoxO3a were ubiquitously expressed in ovarian cancer cell lines." (PMID 26716645, 2016). "In addition, both FoxO1 and FoxO3a have been reported to be involved in cytotoxic stress and drug-resistance induced by chemotherapeutics in ovarian cancers." (PMID 22159921, 2012). "Taken together, these results suggest that FoxO1 and/or FoxO3A may be a novel downstream way in which Mirk serves as an antiapoptotic factor in ovarian cancer cells." (PMID 22159921, 2012). "Clinical ovarian cancer samples were also examined for FOXO1 expression by immunohistochemistry." (PMID 18319717, 2008). "There are far more mechanisms to elucidate although, together with our in vitro data, FOXO1 might be the candidate to predict the chemotherapeutic response and it could be a molecular target for the treatment of drug-resistant ovarian cancers." (PMID 18319717, 2008). "Thus, we speculated that HDAC9 controls FOXO1 activity by regulating the subcellular localization of FOXO1 in ovarian cancer cells." (PMID 35203583, 2022). "However, the role of miR-340 and its potential association with the LGR5 and FOXO1 genes as well as their effects on the drug resistance in ovarian cancer have not been addressed till now." (PMID 33718760, 2021). "However, this phenomenon can be regarded as a sort of vulnerability exploited to restore FoxO signaling with inhibitors of nuclear export, as shown for FoxO1 with the XPO1 inhibitor selinexor in combination with cisplatin in ovarian cancer cells or for FOXO3 with psammaplysene in colon cancer cells." (PMID 30646603, 2019). "Foxo1 could be a molecular target for the treatment of sensitive or drug-resistant ovarian cancers." (PMID 26055813, 2015). "Given the main function of Mirk in ovarian cancer cells in mediating cell survival observed in this study, the mechanisms involved may include FoxO family members, such as FoxO1 and/or FoxO3A as well as their downstream signals, which are constitutively expressed in ovarian cancer cells." (PMID 22159921, 2012). "Furthermore, combined siRNAs of Mirk with FoxO1 and/or FoxO3A led to fewer apoptotic cells and cisplatin sensitivity compared to Mirk siRNA alone, suggesting that FoxO is involved in Mirk-mediated cell survival and chemosensitivity of ovarian cancer." (PMID 22159921, 2012).
ovarian carcinoma (continued). "L. Ma and others found that high expression of ITGA2 can promote ovarian cancer cell proliferation and resistance to paclitaxel through the AKT/FOXO1 signaling axis." (PMID 38751445, 2024). "Recently, a study highlighted that high expression of ITGA2 promotes ovarian cancer cell proliferation and resistance to albumin paclitaxel through the AKT/FOXO1 signaling axis." (PMID 37386391, 2023). "However, the role of FOXO1 in the development of ovarian cancer remains unclear." (PMID 38057816, 2023). "In ovarian carcinoma, XPO1 inhibitor inhibited tumor growth and improved the efficacy of cisplatin by nuclear accumulation of FOXO1." (PMID 34384466, 2021). "In ovarian cancer cells, expressions of ITGA2 enhance AKT phosphorylation and further accelerate the phosphorylation of the oncogenic protein FOXO1." (PMID 32899691, 2020). "In this study, we found that CD83 associated with MAP3K7 and activated MAPK cascades to further regulate FOXO1/p21/CDK2/CCNB1 and STAT3/DKK1 signaling pathways, thus activating proliferation and spheroid formation of ovarian cancer cells." (PMID 32823589, 2020). "Collectively, our study suggests that aberrant expression of ITGA2 increases ovarian cancer cell proliferation and enhances ovarian cancer cell resistance to albumin paclitaxel through the AKT/FOXO1 signaling axis." (PMID 32202508, 2020). "We also found that ITGA2 regulated the phosphorylation of forkhead box O1 (FoxO1) by mediating AKT phosphorylation, which provided a reasonable explanation for ITGA2’s role in ovarian cancer’s resistance to albumin paclitaxel." (PMID 32202508, 2020). "NANOG1 overexpression in ovarian cancer cells has been shown to enhance migration capacity, which is accompanied by decreased E-cadherin, caveolin-1, FOXJ1, and FOXO1 expression." (PMID 26087476, 2015). "In ovarian cancer, CXCR4 was detected among 681 hypo methylated-upregulated genes while PTEN, and FOXO-1 were mentioned among the hypermethylated repressed genes and in vascular smooth muscle cell (SMC), vascular injury increased PTEN/AKT signalling through CXCL12- HIF-1alpha." (PMID 38704478, 2024). "Furthermore, the Wnt/β-catenin signaling pathway has been shown to be involved in OC progression, and miR-27a activates Wnt/β-catenin signaling by targeting FOXO1, which promotes EMT in ovarian cancer." (PMID 39068672, 2024). "However, it remains uncertain how ITGA2 regulates AKT/Foxo1 axis and how ITGA2 is regulated in the ovarian cancer cells." (PMID 33026975, 2020). "Overexpression of ITGA2 promoted in vitro cancer cell aggressiveness and in vivo tumor growth through regulation of the phosphorylation of forkhead box O1 (FoxO1) and AKT phosphorylation, which provided the mechanism for ITGA2-mediated paclitaxel-resistance in ovarian cancer." (PMID 33026975, 2020). "FOXO1, a HEDW genes, effects in many carcinomas including ovarian cancer, it is also related to drug resistance in ovarian cancer, while it is not reported in ovarian cancer concerning methylation of FOXO1." (PMID 32192517, 2020). "Moreover, CD83 functions through the activation of MAP3K7-MEK1/2-ERK1/2 cascades to further regulate downstream FOXO1/p21/CDK2/CCNB1 and STAT3/DKK1 signaling pathways, thus activating proliferation and spheroid formation of ovarian cancer cells, respectively." (PMID 32823589, 2020). "We identify the activated TAK1-MEK1/2-ERK1/2 signaling, increased CDK2/cyclin B1 expression, and reduced FOXO1/p21 levels in CD83-overexpressed ovarian cancer cells, indicating that MAPK-ERK1/2-FOXO1 axis is involved in the activation of ovarian cancer cell proliferation by CD83." (PMID 32823589, 2020). "The role of transcriptional factor FOXO1 in the mechanism of drug-resistance in ovarian cancer has not been elucidated." (PMID 18319717, 2008).
ovarian carcinoma (continued). "Hub genes including TNF, ESR1, MUC1 and FOXO1 might be potential targets for diagnosis or treatment of ovarian cancer in an epigenetic approach, TNF, ESR1 and FOXO1 may serve as potential markers for ovarian cancer prognosis evaluation." (PMID 32192517, 2020).
colorectal cancer (51 papers, 2013 to 2026). A primary or metastatic malignant neoplasm that affects the colon or rectum. "A decreased level of ARHGAP15 expression promotes the development of colorectal cancer via the PTEN/AKT/FOXO1 axis." (PMID 39833662, 2025). "We first compared ROS levels in control and HCT116 (colorectal cancer) cells with FOXO1 knockdown or overexpression." (PMID 41124013, 2025). "The regulation of the PI3K/AKT/FOXO1 signaling pathway has been demonstrated in different types of tumours, including colorectal cancer, pancreatic cancer, and bladder cancer." (PMID 41331197, 2025). "In colorectal cancer, FoxO1 is often downregulated or functionally inactivated in more aggressive tumors, and its higher expression has been correlated with improved patient prognosis." (PMID 41515404, 2025). "The bioinformatic comparative analysis found that PTEN and FOXO1 expressions were downregulated in colorectal cancer tissue compared to normal colon tissue." (PMID 38891994, 2024). "It has been shown that 5-FU therapy increased the expression of chemokine (CCL20) in colorectal carcinoma cells (CRC) in vivo by triggering FOXO1/CEBPB/NF-κB signaling, which aided in the migration of Tregs into TME." (PMID 38347575, 2024). "In colorectal cancer, FOXO1/C/EBPβ/NF-κB signaling is required for CCL20-dependent recruitment of regulatory T cells, which confer chemoresistance to 5-fluorouracil." (PMID 36761942, 2023). "CCL20 secreted by colorectal cancer cells activating FOXO1/CEBPB/NF-κB signaling, promoting the recruitment of Tregs." (PMID 34095111, 2021). "Forkhead box O1 (FOXO1) influencing endothelial growth and proliferation, wound closure and vascular density was also identified as a target molecule of miR-544 in colorectal cancer." (PMID 34066712, 2021). "In concordance, the CCL20 secreted by colorectal cancer (CRC) cells can also recruit regulatory T cells (Tregs) to promote chemoresistance via a FOXO1/CEBPB/NF-κB/CCL20 signaling loop in these cells." (PMID 33483477, 2021). "Exosomes derived from colorectal cancer cells overexpressing miR-183-5p aggravate colorectal cancer by regulating FOXO1." (PMID 34867446, 2021). "In vivo, 5-FU treatment elevated the expression of CCL20 in colorectal cancer cells (CRC) by activating FOXO1/CEBPB/NF-κB signaling, which promoted the recruitment of Tregs within TME." (PMID 34095111, 2021). "MiR-544 promotes cell proliferation and invasion in colorectal cancer progression by targeting forkhead box O1." (PMID 30939162, 2019). "In this study, we found that colorectal cancer cell-derived chemokine (C-C motif) ligand 20 (CCL20) induced recruitment of Tregs via FOXO1/CEBPB/NF-κB signaling, and that Tregs further promoted chemoresistance of CRC." (PMID 31395078, 2019). "These miRNAs targeting FOXO1 to exert their effects on cell apoptosis and proliferation in colorectal cancer, breast cancer and HCC." (PMID 27999212, 2017). "Interestingly, gains and amplifications of FOXO1 are evident in colorectal cancers, and levels of FOXO1 show a moderate increase with advanced tumour stages of colorectal cancer." (PMID 41266617, 2026). "Furthermore, in 4 out of 7 colorectal cancer patients, the mRNA levels of FOXO1 in tumor tissues were much higher than those in the adjacent normal tissues." (PMID 41124013, 2025). "In addition, the up-regulation of miR-183-5p can promote the occurrence of colorectal cancer by regulating FOXO1, proving its potential role as biomarker for the treatment of colorectal cancer." (PMID 36629518, 2023). "The transcriptional activity of genes involved in the autophagy process (LAMP-2, BECN1, PINK1, FOXO1) in colorectal cancer biopsies in four clinical stages of adenocarcinoma (CSI, CSII, CSIII, CSIV) was compared with that of controls (colon samples assessed as histopathologically normal)." (PMID 36830954, 2023).
colorectal cancer (continued). "Moreover, ERK2 regulated the epithelial-to-mesenchymal transition (EMT) plasticity in breast epithelial cells through FoxO1 activation, and p38 activated by anticancer drugs affected colorectal cancer growth via the regulation of FoxO3 nuclear localization." (PMID 36077661, 2022). "As IBD is a risk factor of colorectal cancer, we cautiously speculate that FoxO1 might play a role in the transformation from colitis to colorectal cancer." (PMID 32057181, 2020). "FOXO1 has been described to be a direct target of miR-544 in colorectal cancer development." (PMID 31440517, 2019). "For instance, FOXO1 and FOXO3a are both direct targets of miR-96 in colorectal cancer and HCC." (PMID 27999212, 2017). "This study discovers that SIRT1, a hub gene involved in glucolipid metabolic conversion in colorectal carcinoma (CRC), stimulates CX3CL1 secretion in CRC cells by activating FOXO1." (PMID 39783838, 2025). "In chemo-resistant colorectal cancer, CCL20 recruits Tregs to support the process through the forkhead box protein O1 (FOXO1)/CCAAT/enhancer-binding protein beta (CEBPB)/NF-κB pathway." (PMID 40076892, 2025). "In colorectal cancer, miR-96 seems to contribute to cell growth, and target directly TP53INP1, FOXO1 and FOXO3a53." (PMID 38636197, 2024). "The involvement of FOXO1 in colorectal cancers and KRAS-induced metabolic reprogramming is not well-characterised." (PMID 41266617, 2026). "FoxO family (FOXO1/3/4/6) comprises stress-responsive transcription factors that enforce cell-cycle arrest and apoptosis and are frequently curtailed by hyperactive PI3K–AKT and MAPK signaling in colorectal cancer." (PMID 41411347, 2025). "Colorectal cancer (CRC) cells releasing CCL20 attracted Tregs, fostering chemoresistance through FOXO1/CEBPB/NF-κB signaling, which could be a promising strategy for treating CRC." (PMID 39143228, 2025). "FoxO1/FKHR is a member of the Forkhead box O (FoxO) transcription factor family, with an emerging and context-dependent role in various digestive malignancies, including colorectal carcinoma." (PMID 41515404, 2025). "Furthermore, CEBPB also interacts with FOXO1, NF-kappa B, and CCL20, and FOXO1/CEBPB/NF-kappa B/CCL20 axis has been reported as a target for Colorectal cancer treatment." (PMID 34490085, 2021). "A previous investigation showed that hyperoside has anticancer activity against lung cancer cells by upregulating FoxO1 via CCAT1; additionally, it showed an inhibitory effect against SW620 human colorectal cancer cells via the induction of the p.53 signaling pathway and apoptosis." (PMID 32709119, 2020). "And while Foxo1 is not one of the culprits in the altered version of the pathway, the altered TGF-beta SMAD network is associated with pancreatic cancer and also, with colorectal cancer pathways." (PMID 27602200, 2016).
glioma (49 papers, 2012 to 2025). A benign or malignant brain and spinal cord tumor that arises from glial cells (astrocytes, oligodendrocytes, ependymal cells). "Restoring FOXO1 expression in gliomas can cause cell cycle arrest at the G2/M phase via phosphorylating CDK1 at s249, resulting in hindered cell proliferation and increased apoptosis." (PMID 37821870, 2023). "In this study, we were interested in identifying the role of FOXO1 in glioma and its association with FOXO1." (PMID 35141227, 2021). "The small number of articles reporting on PID1 to date hardly clarifies the role of PID1 in drug resistance in glioma and its association with FOXO1." (PMID 35141227, 2021). "To understand the mechanism underlying FOXO1 functioning in glioma, we continued to explore its target genes." (PMID 35141227, 2021). "FOXO1 is involved in the regulation of cell death and growth of glioma cell lines and has been associated with chemotherapy sensitivity and glial-mesenchymal transition in gliomas." (PMID 32604718, 2020). "These analyses demonstrated that FOXO1 is associated with glioma progression and would be a valuable predictor for the survival of glioma patients." (PMID 27835585, 2016). "The precise mechanism underlying the cancer-suppressive properties of FOXO1 in glioma remains elusive in our further studies." (PMID 27835585, 2016). "Transcription factor forkhead box protein O1 (FOXO1) is located at a convergence point of receptor tyrosine kinase signaling and is also highlighted to be associated with sensitivity to chemotherapy drugs against glioma." (PMID 35141227, 2021). "Glioma-associated nodes in the neighborhood of FOXO1, CARHSP and PBX3." (PMID 28957313, 2017). "High cytoplasmic Foxo1 expression in human gliomas is associated with a higher grade of malignancy." (PMID 27733172, 2016). "Previous studies have reported a decrease in FOXO1 expression in glioma, and our research confirms this trend using online databases and clinical specimens." (PMID 39516471, 2024). "According to above evidence, CARD16 is increased in malignant glioma and functions as a tumor promoter in glioma through enhancing phosphorylation and ubiquitination of FOXO1, and additionally limiting TRAIL-induced apoptosis." (PMID 39516471, 2024). "Here, we present findings that CARD16 plays a pivotal role in proliferation and anti-apoptosis by downregulating the FOXO1/TRAIL pathway in glioma." (PMID 39516471, 2024). "It has been shown that in gliomas OCT4 expression is maintained by the transcription factors FOXO1 and FOXO3 and suppressed by PI3K/Akt/mTOR, and its level is significantly enhanced when PI3K is inhibited simultaneously with mTOR or MEK." (PMID 38392188, 2024). "Collectively, these findings suggest that CARD16 is a tumor-promoting molecular in glioma via downregulating FOXO1/TRAIL axis, and suppressing TRAIL-induced apoptosis." (PMID 39516471, 2024). "FOXO1 was associated with theprognosis of multiple tumors, especially LGG (low grade glioma), OV (ovariancarcinoma), and KIRC (kidney renal clear cell carcinoma)." (PMID 38716982, 2024). "It is noteworthy to mention that some ncRNAs form a positive feedback loop that constantly represses FOXO1 expression, leading to glioma progression." (PMID 37821870, 2023). "For instance, FoxO1 promotes glioma cell proliferation by acting as a transcriptional activator of RFC2." (PMID 37821801, 2023). "This gets more confusing when a recent study revealed that targeting FOXO1 by miR-5188 is necessary for the activation of PI3K/AKT/c-JUN signaling pathway in U87 and U251 glioma cell lines, supporting the tumor-suppressive side of FOXO1." (PMID 37821870, 2023).